HBQ1 (hemoglobin subunit theta 1)
Synonyms: HBQ
Tractability: PROTAC: ubiquitination databases record sites on it.
Gene: Protein-coding gene on chromosome 16 (180,459 to 181,179, forward strand). Ensembl gene ENSG00000086506.
Subcellular location (Human Protein Atlas): Lipid droplets
Gene Ontology:
Molecular function: protein binding; heme binding; oxygen carrier activity; iron ion binding; oxygen binding
Biological process: erythrocyte development; oxygen transport
Cellular component: haptoglobin-hemoglobin complex; hemoglobin complex
Genetic constraint (gnomAD): Loss-of-function variants: 11 observed, 7.02 expected, observed/expected ratio (o/e) 1.57, 90% interval 0.94 to 1.94. That is too few expected variants to judge how well the gene tolerates losing a copy. Missense variants: 216 observed, 155.8 expected, observed/expected ratio (o/e) 1.39, 90% interval 1.24 to 1.55. Synonymous variants: 102 observed, 83.6 expected, observed/expected ratio (o/e) 1.22, 90% interval 1.04 to 1.44.
Homologues: Orthologues: chimpanzee HBQ1 (100% identical), macaque HBQ1 (96% identical), pig HBQ1 (77% identical), mouse Hbq1b (75% identical), guinea pig HBQ1 (71% identical), mouse Hbq1a (67% identical), Drosophila melanogaster glob1 (23% identical), Caenorhabditis elegans glb-34 (20% identical), Caenorhabditis elegans glb-14 (15% identical). Paralogues in human: HBA1 (62% identical), HBA2 (62% identical), HBZ (52% identical), HBM (41% identical), HBD (40% identical), HBG1 (40% identical), HBG2 (40% identical), HBB (39% identical), HBE1 (37% identical), CYGB (33% identical), MB (23% identical).
Diseases named in the same sentence as HBQ1 in open-access papers:
HBQ1 is named in the same sentence as 18 diseases in open-access papers, as found by Europe PMC text mining. Sharing a sentence is not in itself a finding about the gene and the disease. The quoted sentences say what the papers report.
Obesity (3 papers, 2018 to 2023). Accumulation of substantial excess body fat. "Using this approach, we detected rs11863726 in hemoglobin subunit theta 1 (HBQ1), rs328 in lipoprotein lipase (LPL), and rs112984085 in Vav guanine nucleotide exchange factor 3 (VAV3) for T2D and obesity." (PMID 37623486, 2023). "In our study, we observed several highly case-specific variants in genes previously not directly linked to T2D and/or obesity (e.g., TMC8, PCDHA1, PLEKHA5, HBQ1, VAV3, and ADAMTS13)." (PMID 30126146, 2018).
breast carcinoma (1 paper, 2023). "When patients with breast cancer were treated with the combination of bevacizumab and doxorubicin, HBQ1 was often differentially expressed and IGKV1D-8 was primarily involved in immune response." (PMID 37670814, 2023).
Glucose intolerance (1 paper, 2020). Glucose intolerance (GI) can be defined as dysglycemia that comprises both prediabetes and diabetes. "Glucose intolerance was associated with Brevican (Bcan chondroitin sulfate/dermatan sulfate metabolism) and Hbq1a (hemoglobin subunit theta 1, iron and oxygen-binding)." (PMID 32636363, 2020).
iron deficiency (1 paper, 2013). "In category 2, the genes encoding nuclear factor, erythroid-derived 2 (Nfe2); hemoglobin, theta 1 (Hbq1); erythroid associated factor (Eraf); and 2,3-bisphosphoglycerate mutase (Bpgm) were down-regulated only in the case of short-term iron deficiency." (PMID 23755274, 2013).
lung adenocarcinoma (1 paper, 2023). A carcinoma that arises from the lung and is characterized by the presence of malignant glandular epithelial cells. "Our findings highlight the importance of HBQ1 in lung adenocarcinoma and suggest its potential as both a diagnostic marker and a molecular target for therapeutic interventions." (PMID 38067210, 2023). "In summary, our study provides evidence of the novel role of HBQ1 in lung adenocarcinoma; HBQ1 is upregulated in lung adenocarcinoma tissues and its high expression is associated with a poor prognosis in patients with this disease." (PMID 38067210, 2023). "In the present study, we demonstrated for the first time that HBQ1 expression is elevated in lung adenocarcinoma tissues compared to normal lung tissues." (PMID 38067210, 2023). "To further confirm the potential of HBQ1 as a molecular target for lung adenocarcinoma, we established mouse xenograft models by subcutaneously injecting A549 cells with stable HBQ1 knockdown cells." (PMID 38067210, 2023). "In the present study, we performed immunoblotting analysis to investigate the expression of HBQ1 in lung adenocarcinoma cell lines A549 and A427." (PMID 38067210, 2023). "Taken together, these findings support the crucial involvement of HBQ1 in the development and progression of lung adenocarcinoma and its potential as a therapeutic target." (PMID 38067210, 2023). "This study provides preliminary evidence that HBQ1, a hemoglobin α subunit, is expressed in lung adenocarcinoma cells." (PMID 38067210, 2023). "Comparative analysis showed that HBQ1 expression was significantly higher in lung adenocarcinoma tissues compared to normal lung tissues." (PMID 38067210, 2023). "The present study aimed to investigate the role of HBQ1 in lung adenocarcinoma to expand the treatment strategies of the disease using both in vitro and in vivo experiments." (PMID 38067210, 2023). "To investigate the role of HBQ1 in human lung adenocarcinoma cells, we transfected A549 and A427 with either HBQ1 overexpression or HBQ1 knockdown vectors." (PMID 38067210, 2023). "Collectively, our results demonstrate that targeting HBQ1 provides a new therapeutic approach for lung adenocarcinoma treatment." (PMID 38067210, 2023). "HBQ1 knockdown resulted in the inhibition of lung adenocarcinoma growth, demonstrating the potential of HBQ1 as a therapeutic target." (PMID 38067210, 2023). "Our in vivo studies further supported the role of HBQ1 in lung adenocarcinoma." (PMID 38067210, 2023). "We analyzed the association between HBQ1 expression levels and human lung adenocarcinoma and detected a significant upregulation of HBQ1 expression in lung adenocarcinoma tissues compared to normal lung tissues, suggesting its role as an oncogene in lung adenocarcinoma." (PMID 38067210, 2023). "Furthermore, we examined the relationship between HBQ1 expression and clinical outcomes in patients with lung adenocarcinoma." (PMID 38067210, 2023). "We investigated whether HBQ1 expression influences the proliferation of lung adenocarcinoma cells through the regulation of ROS levels." (PMID 38067210, 2023). "However, the functional role of HBQ1 expression in cancer biology, particularly in the development and progression of lung adenocarcinoma, remains to be elucidated." (PMID 38067210, 2023). "Based on this evidence, we investigated whether HBQ1 regulates cell proliferation and found that HBQ1 overexpression significantly increased lung adenocarcinoma cell proliferation, whereas HBQ1 knockdown decreased it." (PMID 38067210, 2023). "This specific expression pattern makes HBQ1 an attractive option for reducing ROS levels in lung adenocarcinoma without affecting erythrocyte function." (PMID 38067210, 2023). "The present study aimed to investigate the role of hemoglobin subunit theta 1 (HBQ1), an α subunit of hemoglobin whose expression has recently been reported in non-erythroid cells, in lung adenocarcinoma." (PMID 38067210, 2023).
lung carcinoma (1 paper, 2023). "Furthermore, we examined the relationship between HBQ1 expression and clinical outcomes in patients with lung cancer." (PMID 38067210, 2023).
α-thalassemia (1 paper, 2025). "This region includes HBM, HBA2, HBA1 and HBQ1, which is associated with the pathogenesis of α-thalassemia." (PMID 41444645, 2025).
tumor (3 papers, 2021 to 2023). "In vivo studies support HBQ1’s role in tumor growth, suggesting it as a potential therapeutic target." (PMID 38067210, 2023). "Hemoglobin subunit theta 1 (HBQ1) is often used as an indicator related to tumor metabolism." (PMID 37670814, 2023). "In addition, our xenograft results also showed that HBQ1 knockdown inhibited tumor growth in vivo." (PMID 38067210, 2023). "Furthermore, HBQ1 knockdown effectively suppressed tumor growth in vivo." (PMID 38067210, 2023). "Some genes, like KHNYN, HBQ1, SCD5 and FLVCR2, may play roles in tumorigenesis, metabolism or tumor therapy." (PMID 34568059, 2021).
cancer (2 papers, 2017 to 2023). A tumor composed of atypical neoplastic, often pleomorphic cells that invade other tissues. "Other genes, such as ALOXE3, HBQ1, KREMEN2, SYT13, DOK7, CDC5L, and FBXO6, have been reported in several cancers." (PMID 28404969, 2017). "In contrast, HBQ1, which has been reported to not be expressed in erythrocyte tissues, is a promising candidate for ROS-targeted cancer therapy." (PMID 38067210, 2023).
adenocarcinoma (1 paper, 2023). A common cancer characterized by the presence of malignant glandular cells. "Elevated HBQ1 expression in adenocarcinoma tissues correlates with poor survival." (PMID 38067210, 2023). "However, our data do not show any significant impact on the invasion capacity of adenocarcinoma cell lines when HBQ1 expression is regulated." (PMID 38067210, 2023).
neurological disorders (1 paper, 2021). "They include characteristic genes, Prnp, Cct4, Vegfd (Figf), Map9 (Mtap9), Pik3cg, Zfand5, Endog, and Hbq1, which are reportedly associated with AD, CJD, and/or related neurological disorders." (PMID 34959983, 2021).
HBQ1 also shares sentences with these, for which no sentence is quoted: malaria (2 papers); anemia (1); endocrine disorders (1); glioma (1); malnutrition (1); migraine (1); tick-borne diseases (1).